KRAS (KRas proto-oncogene, GTPase)
Diseases named in the same sentence as KRAS in open-access papers (continued):
Sharing a sentence is not in itself a finding about the gene and the disease.
metastasis (38 papers, 2009 to 2026). The spread or migration of cancer cells from one part of the body (where they first appeared) to another. "Lung metastasis was more common at diagnosis in patients whose primary tumor carried a KRAS mutation and was more likely to develop during the disease course." (PMID 40549756, 2025). "We then examined the potential impact of molecular alterations in patients with liver metastasis specifically, and the presence of KRAS mutations significantly predicted worse overall survival with a hazard ratio of 2.01 (p < 0.001)." (PMID 41301041, 2025). "In the KRAS-mutation group, lung metastasis (21.7%, P = 0.012) and brain metastasis (23.3%, P = 0.001) were more common." (PMID 39464712, 2024). "In the KRAS mutation group, 120 cases (54.2%) developed tumor metastasis, and the frequent sites were lung metastasis (26 cases, 21.7%, P = 0.012) and brain metastasis (27 cases, 23.3%, P = 0.001)." (PMID 39464712, 2024). "KRAS mutations were detected in 82.3% of patients with liver or lung metastasis, which was consistent with other reports." (PMID 36810451, 2023). "In patients with lung metastasis only, blood and tissue samples had different rates of KRAS mutations." (PMID 37751775, 2023). "KRAS codon 12 mutation was remarkably associated with peritoneal metastasis, liver-peritoneum metastases, and multiorgan metastases compared to all wild types." (PMID 35531124, 2022). "Both the CRP SNP rs7553007 and KRAS/BRAF mutations were independent prognostic factors for CRC patients with synchronous liver metastasis." (PMID 23755178, 2014). "Finally, one analysis demonstrated significantly worse survival for SMARCA4/KRAS-co-mutated patients as they presented at a higher rate of Stage IV NSCLC with a significantly higher propensity of brain or liver metastasis." (PMID 39063938, 2024). "In addition, we identified the same KRAS mutation in the biopsied liver metastasis and resected right ovarian metastasis." (PMID 34367398, 2021). "In addition to hepatic steatosis, we also found that depth of tumor invasion, number of liver metastasis, preoperative chemotherapy and KRAS mutation was significantly associated with overall RFS." (PMID 33767997, 2021). "In addition, liver metastasis, lung metastasis, high ALP level and high CEA level were frequently observed at the time of bone metastasis in the group with KRAS mutation." (PMID 33273596, 2020). "The correlation between KRAS mutation and radiosensitivity for patients with lung metastasis is still unknown." (PMID 30305131, 2018). "High Cdc42 expression was significantly associated with Kirsten rat sarcoma viral oncogene homolog (KRAS) wild-type status (p = 0.001), lymph node metastasis (p = 0.039), and perineural invasion (p = 0.021)." (PMID 42194810, 2026). "The overexpression of HOXA7 showed a positive correlation with tumor differentiation, lymph node metastasis, distant metastasis, high tumor nodule metastasis (TNM) stage, and KRAS mutation." (PMID 35183163, 2022). "The results showed that the presence of the A-allele at CRP SNP rs7553007 (HR = 1.101; 95% CI = 1.011–1.200; P = 0.027) and KRAS/BRAF mutations (HR = 2.377; 95% CI = 1.293–4.368; P = 0.005) were independent prognostic factors in CRC patients with synchronous liver metastasis." (PMID 23755178, 2014). "In the present study, multivariate analysis identified synchronous metastasis and liver metastasis as independent predictors of poor prognosis, whereas the KRAS mutation status did not influence the prognosis of the study population (P = 0.078)." (PMID 29147353, 2013). "Furthermore, the CRP SNP rs7553007 (hazard ratio [HR] = 1.101; 95% confidence interval [CI] = 1.011–1.200; P = 0.027) and KRAS/BRAF mutations (HR = 2.377; 95% CI = 1.293–4.368; P = 0.005) remained predictive for the CSS of CRC patients with synchronous liver metastasis in multivariate analysis." (PMID 23755178, 2014).
metastasis (continued). "The prevalence of CNS metastasis in patients with specific genomic alterations was the following: ALK (34.9%), RET (32.2%), KRAS (30.2%), EGFR (29.4%), and wild type (28.8%)." (PMID 40423053, 2025). "Data showed that the TCAF2+ TPC ratio was associated with liver metastasis and TNM stage, but not with KRAS or BRAF mutations." (PMID 37635201, 2023). "MAZ expression was elevated in PCa tissues with bone metastasis (T4–6) compared with expression in PCa tissues without bone metastasis and was further increased in metastatic bone tissues (T7–9); consistently, protein expression of KRas and activated RalA exhibited the same pattern." (PMID 31488180, 2019). "Statistically significant relationships were present between KRAS exon 2 and mucinous morphology, PIK3CA and absence of perineural invasion, BRAF and tumor differentiation/localization, MutS homolog 3 (MSH3) and tumor diameter, and BRCA2 and absence of lymph node metastasis." (PMID 37737217, 2023).
neuroblastoma (38 papers, 2006 to 2025). Neuroblastoma (NB) is the most common solid, extracranial childhood tumor. "Herein, we demonstrate this approach using an enumeration of each position in the coding region of KRAS (S_Table 7), mutations in which have been implicated in neuroblastoma." (PMID 34551708, 2021). "Other rat sarcoma (RAS) mutations (specifically KRAS exon 3 and 4, and neuroblastoma (N]RAS) and v-raf murine sarcoma viral oncogene homolog B1 (BRAF) mutations may similarly reduce the benefit of anti-EGFR therapies." (PMID 34298750, 2021). "Moreover, MEKi treatment of a KRAS mutated neuroblastoma cell line NBEB (KRAS_G12D) also increased CASZ1 expression." (PMID 32060262, 2020). "Four neuroblastoma cell lines were included based on the presence of the most common mutations affecting the RAS-MAPK pathway, RAS (KRAS in SJNB8 and NRAS in SKNAS), NF1 (SKNBE) and ALK (KCNR)." (PMID 36895472, 2023). "A previous study has reported that DJ-1 is up-regulated in human neuroblastoma cells by the activation of the MAP kinase pathway which is downstream to KRAS protein activation." (PMID 29507676, 2018). "Sequencing analysis of MM patient samples has shown that the Kirsten RAS (KRAS) oncogene is the most commonly mutated gene (36%) in the disease, followed by the neuroblastoma RAS (NRAS) (20%), with frequent co-existence of one or more variants in both KRAS and NRAS cancer-driver genes." (PMID 36523963, 2022). "Although autophagy has been proposed as a mechanism of Id1 degradation in neuroblastoma cells, our data indicate that the autophagy inhibitor CQ does not affect the trametinib-mediated Id1 downregulation in KRAS-mutant LUAD cells." (PMID 38643157, 2024). "However, to our knowledge, recurrent focal amplifications of MYC, ZFHX3, KRAS, RRAS2, and CYTH1 have not been reported in neuroblastoma primary tumors before." (PMID 28924153, 2017).
lymphoma (37 papers, 2008 to 2026). A malignant (clonal) proliferation of B- lymphocytes or T- lymphocytes which involves the lymph nodes, bone marrow and/or extranodal sites. "Among these hotspot mutations, A146 substitution mutations (A146X) occur relatively infrequently, except for haematopoietic and lymphoid cancers, suggesting that A146X causes intrinsically distinct KRAS signalling compared to other KRAS oncogenic alleles." (PMID 41750275, 2026). "Some institutes have used this method to detect somatic mutations including KRAS, XPO1, STAT6 and so on in some solid tumors and lymphomas." (PMID 32284750, 2020). "Furthermore, JQ1 in combination with anti-PD-1 antibody enhances antitumor responses in mice bearing Myc-driven lymphomas and KRAS-driven NSCLC." (PMID 31258527, 2019). "The mitochondrial remodelling in KRAS mutated–BRAF wild-type CRC agree with Warburg’s hypothesis, suggesting that the scenario might be different to that observed in other tumours, as in the case of the relevant role of OXPHOS in lymphomas." (PMID 34439343, 2021). "We did not identify either PTPN11 nor KRAS mutations in any of the lymphoma samples." (PMID 31277422, 2019). "Not surprisingly, activated STAT3 alone can also increase PD-L1 expression by directly acting on the promoter of PD-L1 in HNSCC and lymphoma cells, and STAT3 silencing leads to the downregulation of PD-L1 in ALK-negative ALCL cells and KRAS-mutant NSCLC cells." (PMID 31258527, 2019). "A similar pattern was observed in the lymphoma cell line SUD-DHL-4 V, which does not harbor mutations in KRAS and BRAF." (PMID 26799289, 2016).
multiple myeloma (35 papers, 1995 to 2026). "Thus, in patient #1, with a single nucleotide deletion (c.286 delT) in the KRAS gene in addition to cytogenetic aberrations, high LDH activity, an advanced ISS stage, concomitant AL-amyloidosis was observed, and the course of the disease was refractory and recurrent." (PMID 39273371, 2024).
breast tumors (34 papers, 2005 to 2025). "KRAS mutations with predominantly G12 codon mutations occur in 4% of approximately 500 primary breast tumors examined." (PMID 36358741, 2022). "We aimed to study the mutation frequency of KRAS in that subtype of breast tumors to provide a molecular basis for the evaluation of anti-EGFR therapies." (PMID 20385028, 2010). "Another explanation could involve reduced expression of let-7 miRNA family members in KRAS variant-associated breast tumors." (PMID 22436609, 2012). "We further evaluated whether the KRAS variant associates with a particular breast tumor characteristic." (PMID 22436609, 2012). "Although KRAS is mutated in only a minor fraction of breast tumors (5%), about 60% of the basal-like subtype express EGFR and, therefore could be targeted by EGFR inhibitors." (PMID 20385028, 2010). "Thus, breast tumors with KRAS codon 12 mutations seem to present a worse prognosis." (PMID 23555992, 2013). "We observed a different pattern in breast tumors that metastasize to lung and harbor a mutation in KEAP1, KRAS, STK11, or EGFR." (PMID 32374727, 2020). "The present analysis, on the other hand, revealed that HRT use in women carrying the KRAS variant allele is associated with HER2 overexpressed and poorly-differentiated breast tumors, both indicators of a worse prognosis." (PMID 22436609, 2012). "All these data suggests that deregulation of miRNAs would be a mechanism to explain KRAS overexpression in breast tumors." (PMID 22701724, 2012). "Although little is known about the precise role of KRAS mutations in progression of BC, it is well-established that PI3K/AKT/PTEN pathway is under control of KRAS activity and that abnormal activation of this oncogenic pathway promotes breast tumor growth and invasion." (PMID 36358741, 2022). "While the mechanism seems to vary between tissues, the connection between increased Ras/MAPK activity and MDSC recruitment appears to be conserved, because our data suggest that MEK activation downstream of oncogenic KRAS drives MDSC recruitment to breast tumors." (PMID 32634121, 2020). "In postmenopausal women using HRT, the KRAS variant might lead to HER2 overexpressed and poorly-differentiated breast tumors, both indicators of a worse prognosis." (PMID 22436609, 2012). "Now, we investigated whether miR-30c could be regulating KRAS expression in hereditary breast tumors." (PMID 22701724, 2012). "Interestingly, KRAS was found to be a target of multiple miRNAs found to be down-regulated in breast tumors." (PMID 22701724, 2012). "In addition, the other KRAS regulating miRNAs, let-7 and miRNA-143 were previously found to be significantly down-regulated in breast tumors, while miR-96 regulated KRAS in pancreatic tumors." (PMID 22701724, 2012). "This study indicates that KRAS mutations are very infrequent in triple-negative breast tumors and that EGFR inhibitors may be of potential benefit in the treatment of basal-like breast tumors, which overexpress EGFR in about 60% of all cases." (PMID 20385028, 2010). "Therefore, coordinated down-regulation of miRNAs found in breast tumors would be not only affecting KRAS oncogene expression but also may be targeting other genes of the KRAS/MAPK signaling pathway to cooperatively activate tumorigenic downstream signals." (PMID 22701724, 2012). "Although there was not a substantial change in KRAS mRNA, Paranjape and colleagues reported an enrichment of both NRAS mutant and MAPK activation signatures in breast tumors that had the KRAS variant." (PMID 22436609, 2012).
breast tumors (continued). "Furthermore, target inhibition does not necessarily correlate directly with efficacy, and O'Brien and colleagues have demonstrated that there was no marked tumour growth inhibition of KRAS mutant MDA-MB-231 breast tumour xenografts despite pronounced inhibition of AKT phosphorylation." (PMID 24339963, 2013). "Since we found no incidence of oncogenic KRAS mutations in basal-like tumors, our results indicates that therapies based on EGFR inhibition may be of benefit in the treatment of this particularly agressive subtype of breast tumors." (PMID 20385028, 2010).
esophageal cancer (32 papers, 2002 to 2025). A primary or metastatic malignant neoplasm involving the esophagus. "Gastrointestinal cancers (including CRC and cancers of the esophagus, stomach, small bowel) also share a similar profile where KRAS G12D and G12V were the top two common variants." (PMID 36494601, 2022). "In this study, we screened 64 ESCC tissue specimens for PD-L1 expression, HPV infection, MSI/dMMR, and mutations in the KRAS, BRAF, or PIK3CA genes to determine their prognostic value in esophageal cancers." (PMID 33054840, 2020). "In conclusion, the present study demonstrated that the expression level of miR-27a was low in ESCC and that miR-27a directly targets the KRAS gene, resulting in inhibited cell proliferation in esophageal cancer." (PMID 25436011, 2015). "Druggable target: Some of the ongoing clinical trials examine LY4066434, a Pan-KRAS inhibitor (phase 1, NCT06607185) for advanced solid tumors, as well as BI 3706674 (phase 1, NCT06056024) in patients with gastric or esophageal cancer that present KRAS amplification." (PMID 41369383, 2025). "Additionally, similar to the correlation observed between KIAA1522 and KRAS and MEK, increased ERK activity has been linked to KIAA1522 overexpression and is associated with tumorigenesis and metastasis in esophageal cancer cells." (PMID 37746394, 2023). "For example, 95% of KRAS alterations were missense oncogenic alterations primarily in hotspot codons such as G12, G13, Q61, Q22, A59, K117, and A146 while 5% of the tumors harbored KRAS amplifications, primarily identified in esophageal cancer." (PMID 33889297, 2021). "In addition, it is noteworthy that our previous studies showed that miR193b can induce apoptosis in esophageal cancer cells and validated KRAS as its target." (PMID 32596290, 2020). "In this study, PIK3CA mutation was detected in 12.5% of esophageal cancers and was associated with female or younger patients (≤60 years) lacking mutations in the KRAS and BRAF genes." (PMID 33054840, 2020). "No KRAS mutations were detected in the primary oesophageal cancer cases." (PMID 39484039, 2024). "However, KRAS and NRAS mutations are rarely observed in esophageal cancer." (PMID 28038457, 2017). "Given that predictive markers for other epithelial cancers such as mutations in KRAS, EGFR or BRAF are rarely detected in esophageal cancers, EGFR expression has been predominantly investigated for its potentiality of predicting treatment outcome for esophageal cancers." (PMID 26124180, 2015). "According to our study, anti-KRas antibodies have no prognostic value in esophageal carcinoma, which could be linked to the low percentage of ras mutations in this cancer." (PMID 22448886, 2012). "For example, approximately 45% of driver events in esophageal cancer included focal amplifications in cell cycle genes such as CCND1/2/3 and CDK4/6/9, in addition to amplifications in ERBB2, KRAS, MYC." (PMID 33889297, 2021).
esophageal cancer (continued). "Esophageal carcinoma (adenocarcinoma and SCC; 4/163 = 2.5%), stomach adenocarcinoma (9/375 = 2.5%), and ovarian serous cystadenocarcinoma (7/381 = 2%) showed the highest frequencies of KRAS WT amplification (relative CN > 7)." (PMID 39711431, 2025). "In our series anti-KRas antibodies had no prognostic impact on esophageal cancers." (PMID 22448886, 2012).